SOX2 (SRY-box transcription factor 2)
Diseases named in the same sentence as SOX2 in open-access papers (continued):
Sharing a sentence is not in itself a finding about the gene and the disease.
cancer (continued). "Amongst them, 33 (25.2%) have been reported as GBM-related (e.g., EGFR, PTEN, MTOR) and 29 (22.1%) as cancer-associated genes (e.g., AGAP2, SOX2)." (PMID 38724522, 2024). "While multiple studies have identified SOX2 as a crucial factor in controlling CSC-like properties in various cancer types, the precise role of SOX2 in specific cancers remains controversial." (PMID 38334608, 2024). "Nanog is involved in cancer cell self-renewal regulation and differentiation, while SOX2 and Oct4 are involved in the maintenance of pluripotency in embryonic stem cells." (PMID 38612715, 2024). "SOX2-induced inhibition of Notch signaling in NOTCH-driven TNBC is associated with EMT and cancer stem cell features." (PMID 39478150, 2024). "Our findings suggest that SOX2 is positively correlated with most immunomodulatory genes and the immune checkpoints in the pan-cancer analysis." (PMID 38164286, 2024). "Previous reports have documented conflicting functional effects of SOX2, even within identical cancer types." (PMID 38334608, 2024). "SOX2 plays a crucial role in the early development of ESCs and cancer progression, belonging to the SOX gene family characterized by high mobility group (HMG) domain." (PMID 38561775, 2024). "Collectively, these findings suggest that betalains have significant anticancer potential, demonstrating effects such as apoptosis induction, the inhibition of cancer cell proliferation, and the modulation of key signaling pathways like NF-kB and Stat3/Sox2." (PMID 39682981, 2024). "SOX2 is an oncogene that plays a pivotal role in cancer cell progression and resistance against various therapeutic interventions." (PMID 38786085, 2024). "As a novel SPOP substrate, STAT3 drives a battery of genes involved in cancer stemness maintenance, including SOX2." (PMID 39479456, 2024). "SOX2 overexpression is strongly associated with CSC, EMT, poor prognosis, and chemoresistance in numerous human cancers." (PMID 39334449, 2024). "In another cell cluster, we also discovered the high expression of well-known cancer stem cell markers SOX2 and EGFR (Epidermal Growth Factor Receptor), indicating abnormal proliferation and malignancy in these cell clusters." (PMID 39257581, 2024). "Targeting BCAT1 to reduce its expression has been shown to inhibit metastatic spread and alter the behavior of cancer cells, implicating the modulation of factors such as SOX2 in cancer progression." (PMID 38607736, 2024). "Glioblastoma cell lines T731 and T653 were reprogrammed with Oct4, Sox2, and Klf4 to derive induced pluripotent cancer cells, and the use of a small molecule, PD98059, was shown to increase reprogramming efficiency." (PMID 38247819, 2024). "Given the contradictory prognostic impact of SOX2 expression reported in some cancer types, we wondered about its knockout effect on proliferation and characteristics in LUAD cells." (PMID 38334608, 2024). "Subsequently, this work examined MIR‐766‐3P's impact on cancer stem cell (CSC) marker levels and genes associated with CSC, like OCT4, CD133, SOX2, and NANOG." (PMID 39692209, 2024). "Although SOX2 is a transcription factor, its expression in the cytoplasm has been described in both embryonic and cancer stem cells." (PMID 39201406, 2024). "This is consistent with previous studies that showed the decrease in cancer stem cell factors, such as Oct4, Sox2, and Nanog due to cancer therapy, including chemoradiotherapy or radiation therapy." (PMID 39272290, 2024). "The roles of SOX2 in enhancing angiogenesis in cancers and the wound healing process have also been reported." (PMID 39133273, 2024). "Nanog, OCT4, SOX2 are recognized as key stem cell regulators that maintain the ability of stem cells to self-renew, proliferate and differentiate, transforming cancer cells into a stem cell-like phenotype." (PMID 38819228, 2024). "The pluripotent transcription factors KLF4, NANOG, OCT4, and SOX2 are essential for maintaining cell stemness in cancer." (PMID 38233377, 2024).
cancer (continued). "Since the expression level of SOX2 is an important predictive marker for successful virotherapy, it is important to understand the fundamental mechanisms of the role of SOX2 in the dynamics of cancer stem cells and Zika viruses." (PMID 40342640, 2024). "Over-expression of SOX2 promotes the cancer stem cell phenotype denoted by self-renewal, metastasis, and drug resistance." (PMID 39768557, 2024). "Reprogramming transcription factors (e.g., Oct4 and Sox2) are over-expressed in neoplastic stem-like cells, including GSCs, and function to generate and/or maintain the cancer stem-like phenotype." (PMID 39796709, 2024). "Previous studies have shown that treatment of cancers with PVD, an inhibitor of SOX2 can affect the growth and drug resistance of the cancer cells." (PMID 37298099, 2023). "Sox2 plays a role during all stages of carcinogenesis including cancer cell proliferation, migration, invasion, and metastasis." (PMID 37483598, 2023). "Numerous studies indicated higher expression of SOX2 to correlate with poor prognosis in multiple cancers, including BC." (PMID 37438342, 2023). "MCF7/Zeb1 cells were transduced with this lentiviral vector to select for the population of cancer cells enriched in Oct4/Sox2 stem factors." (PMID 37372954, 2023). "SOX2 is the centre of the transcriptional network influencing pluripotency and is essential in formation of cancer stem cells and resistance to treatment." (PMID 36936374, 2023). "Studies have uncovered the important role that SOX2 has in cancer cell proliferation, anti-apoptotic properties and cell invasion in a variety of cancers." (PMID 36980876, 2023). "A new model system to isolate stem-like cancer cells was recently developed based on the functional transcriptional activity of SOX-2." (PMID 37176108, 2023). "By contrast, Fer-1 rescued the alterations in markers of ferroptosis (GPX4 and SLC7A11) and cancer cell stemness (Oct4 and Sox2) induced by JYQHD." (PMID 37700383, 2023). "To further investigate the relevance of the SOX2/FOSL2 axis in disease aggressiveness, we extracted the SOX2 segment mean from all cancer entities and determined a threshold associated with better overall survival." (PMID 36932385, 2023). "TAB182 KD increased the expression levels of cancer stem cell-related proteins, SOX2 and Slug, using Simple Western assay." (PMID 37953246, 2023). "Our work therefor provides the mechanistic basis of these observations as well as a cancer overarching implication of SOX2/FOSL2 in driving cancer aggressiveness." (PMID 36932385, 2023). "There is not a consensus marker for cancer stem cells (CSC); therefore, several pluripotent stem cell transcription factors, such as sox2, Oct4, and Nanog, are commonly applied to measure cancer stemness." (PMID 37370863, 2023). "This process also requires the expression of cancer stemness TFs OCT-4, NANOG, and SOX2, emphasizing the role of TFs in cancer cell-myCAF crosstalk, as also demonstrated in MBA-MB-231 breast cancer and HepG2 hepatocellular carcinoma cells." (PMID 38124183, 2023). "In contrast to LUAD, LUSC samples were more abundant in CDKN2A (14.65% vs 1.05%), proliferating (26.33% vs 1.73%), and SOX2 cancer cells (43.89% vs 24.18%)." (PMID 36973297, 2023). "To determine if ERβ and its variants have any effect on the stemness of the cancer cells, we analyzed expression of Yamanaka factors OCT4, SOX2, and KLF4 that induce pluripotency in normal cells." (PMID 36982940, 2023). "TM4SF1 promoted epithelial–mesenchymal transition (EMT) and cancer stemness via the Wnt/β-catenin/SOX2 pathway in CRC, which revealed that TM4SF1 modulated SOX2 expression in a Wnt/β-catenin activation-dependent manner." (PMID 36766788, 2023). "ChIP-seq Enrichment Analysis (ChEA) for these up-regulated genes in the KO cells demonstrated over-representation of transcription factors of SUZ12, AR, Nrf2, SMAD4, as well as SOX2 and Nanog important for the stem cells and cancer stem cells." (PMID 37151890, 2023).
cancer (continued). "ALK immunoreactivity was also significantly associated with expression of cancer stem cell (CSC)-related molecules (cytoplasmic CD133, ALDH1, Sox2) and neuroendocrine markers (CD56 and synaptophysin)." (PMID 37592266, 2023). "Overexpression of NF-YAx activates key genes -Nestin, SOX2, Nanog- that lead to selection of NB cancer stem cells." (PMID 36707502, 2023). "Given the evidence that the SRR124–134 cluster is driving SOX2 overexpression in cancer patient tumors, we investigated which transcription factors regulate this cluster in BRCA, LUAD and LUSC tumors from TCGA." (PMID 37738673, 2023). "Integrated multi-omic analysis identified that the transcription factor gene SOX2 was amplified and transcriptionally upregulated in aggressive cancers." (PMID 36932385, 2023). "For example, the helicase DNA-binding protein (CHD4) suppresses the expression of Sox2 and regulates cancer stem cells, targeting different molecules such as SANIL1, CCND1, CCND3, P21, P7, and c-Myc." (PMID 37761837, 2023). "Deletion of the SRR124–134 cluster disrupts expression of the SOX2 oncogene, dysregulates genome-wide transcription and chromatin accessibility and reduces the ability of cancer cells to form colonies in vitro." (PMID 37738673, 2023). "SOX2 is a transcription factor involved in cancer progression that promotes cancer cell migration, invasion, and proliferation." (PMID 37138865, 2023). "The role of m6A in cancer is bidirectional; for instance, in colorectal cancer, SOX2 exerts a pro-cancer effect via METTL3-catalyzed methylation." (PMID 36830673, 2023). "In the cancer context, SOX2 is a well-characterized key factor essential for cancer stem cell (CSC) self-renewal and reprogramming." (PMID 37393309, 2023). "In melanoma cell lines, KMT2A knockdown markedly decreased the expression of cancer stem cell markers, namely Nanog, Oct-4, and Sox-2, and significantly repressed the tumorsphere formation ability." (PMID 36674511, 2023). "Simultaneous delivery to non-CSCs and breast CSCs, ↑ cellular uptake ↑ CSCs differentiation, ↓ self-renewal capacity, ↑ sensitivity to chemotherapy ↓ Nanog, ↓ Sox2, ↓ Oct4, ↓ cancer initiating activity of CSCs." (PMID 37033601, 2023). "The gene amplification and overexpression of transcription factor SOX-2 plays an important role in cancer progression and the metastasis of various cancers, including CaP." (PMID 37895357, 2023). "Pioneer transcription factors (TFs) like SOX2 are vital for stemness and cancer through enhancing gene expression within transcriptional condensates formed with coactivators, RNAs and mediators on super-enhancers (SEs)." (PMID 37930832, 2023). "Sox2 was present in at least 25 types of cancers, including breast, gastric, and pancreatic cancers; adenocarcinoma of the ampulla of Vater; malignant gliomas; and other brain tumors." (PMID 37761837, 2023). "In previous studies, it has been reported that YBX1 promoted the growth of cancer stem cell population and seemed to modulate the expression of numerous stemness genes, including SOX2, CD10, CD24, and CD44." (PMID 36805592, 2023). "SETDB2 interacts with ΔNp63 and methylates and stabilizes the ΔNp63 protein, and SOX2 activates ΔNp63 by directly binding the enhancer site and rescued the cancer stem cell maintenance." (PMID 37182132, 2023). "For example, curcumin reduces the metastatic properties of cancer cells by influencing EMT-related proteins such as vimentin, fibronectin, β-catenin, and E-cadherin as well as genes expressed in cancer stem cells such as Oct4, Nanog, and Sox2." (PMID 37371804, 2023). "Next, we validated the role of cancer stem cell markers in spheroid formation by evaluating the expression of the purported stem cell markers, Sox2, Shh, and Nanog." (PMID 36980879, 2023). "Presence of many SOX2-enriched SEs near stemness genes highlights the potential of targeting the SOX2-dependent transcriptional activation process for controlling cell differentiation and cancer stemness." (PMID 37930832, 2023).
cancer (continued). "MiR-381 levels have been demonstrated to be inversely linked with the expression of defined cancer stem cell marker genes, including CD44, Sox2, Oct4, Nanog, and ALDH1 in RCC tissues." (PMID 37965067, 2023). "On the contrary, SMARCA4 interacts with TGFB2-AS1 long non-coding RNA in breast cancer, resulting in transcriptional repression of TGFB2 and SOX2, and therefore, leading to attenuation of TGF-β signaling and loss of cancer stem cell-like characteristics." (PMID 36674511, 2023). "NEAT1 knockdown is implicated in cancer cell sensitization to chemotherapy, and attenuation of SOX2+ cancer cell population." (PMID 37310654, 2023). "SOR reduced the level of SOX-2 that maintenance of cancer stemness and tumorigenicity, and TNF-α and IL-1β levels." (PMID 37259369, 2023). "It has been reported that SOX2 is involved in stemness, chemoresistance, metastasis and recurrence of cancer." (PMID 37147666, 2023). "We found frequent Sox2 expression in a series of PDCs, possibly in line with the role of Sox2 in cancer stem cells." (PMID 37888115, 2023). "These genes included many of the bona fide pluripotency-related genes including Sox2, which was observed in cancer cells derived from patients and Nanog." (PMID 36156096, 2023). "UsingA549 cancer cells, which express the core stem factors Oct4 and Sox2, weevaluated the effect of these drugs on the survival and preservation of theoriginal properties of cancer stem cells." (PMID 37153502, 2023). "To assess the presence of GBM cancer stem cells we used immunofluorescence staining for the cancer stem cell marker SOX2." (PMID 36632958, 2023). "Apart from SOX2, other genes involved in cancer aggressiveness, such as ZIC5, FAM83A, AADAC and MYEOV, were among the top most significantly associated genes and were associated with patient outcome." (PMID 36932385, 2023). "In these studies, the levels of myCAF phenotype markers, α-SMA, TenC and Vim, and the cancer stemness markers sox2, Oct4, and Nanog were measured in the MSCs and cancer cells." (PMID 37370863, 2023). "One of the family members SOX2 is overexpressed in cancers of the breast, lung, ovary, colon and prostate and its expression is positively correlated with poor patient outcomes." (PMID 37298099, 2023). "HIF-1/2α can mediate SOX2 mRNA demethylation to inhibit the proliferation and stemness in cancer stem cells." (PMID 37016436, 2023). "SOX2, a pioneer TF found in SEs of pluripotent and cancer stem cells, initiates SE-mediated transcription by binding to nucleosomes, though the mechanism isn’t fully understood." (PMID 37930832, 2023). "SOX2 seems to play a key role in the development of cancers of various areas like from breast, colorectum, skin, head, and neck, including the oral cavity as well." (PMID 37859926, 2023). "Moreover, AKT-driven phosphorylation was reported to maintain the stability and nuclear localization of SOX2 protein, which is functionally associates with enhanced cell proliferation and anti-apoptosis, thereby regulating clonogenicity and tumorigenicity in cancer." (PMID 37809806, 2023). "Low expression of RBBP4 no longer inhibits E2F1, allowing for increased expression of downstream genes of E2F1 such as OCT4 and SOX2 that maintain cancer cell stemness." (PMID 38028543, 2023). "VEGFA promotes cancer cell renewal, cell migration, invasion and metastasis through induction of SOX-2, which in turn activates SNAI2, an EMT transcription factor." (PMID 37173939, 2023). "SOX2 is a transcription factor crucial for the maintenance of stem cell pluripotency, and its overexpression has been found in several cancer tissues and cells." (PMID 37238229, 2023). "For example, genes encoding chromatin regulators involved in pluripotency, OCT4, SOX2, KLF4, NANOG, and LIN28, are rarely mutated, but frequently overexpressed in cancer, thus rendering pharmacologic interventions challenging." (PMID 36919699, 2023).
cancer (continued). "increased expression of downstream genes of E2F1 such as OCT4 and SOX2 maintain cancer cell stemness." (PMID 38028543, 2023). "The pluripotency markers NANOG and the Yamanaka factors OCT4, SOX2, KLF4 and c-MYC have previously been shown to be linked with enhanced cancer stem cell properties in cancer cells." (PMID 37950151, 2023). "The results showed that HDAC3 silencing reduced the phosphorylation of CDK1 Y15 and STAT3 Y705 followed by reduction of CD44 and Sox2, which resulted in the impairment of cancer cell stemness." (PMID 37743465, 2023). "The GREAT analysis showed enrichment of both positively and negatively age-related CpG sites in mortality or aging gene sets, cancer and targets of three Yamanaka factors: SOX2, MYC and OCT4." (PMID 37563227, 2023). "Embryonic stem cell (ESC) transcription factors such as NANOG, Oct-4, KLF4, and SOX-2 are reported to be involved in the stemness features of cancer cells, including in the process of dormancy/reactivation induced by chemotherapy." (PMID 37176108, 2023). "Starting from alveolar cells, the cells transformed into pathological alveolar cells, CXCL1, LAMC2, CDKN2A, proliferating, and SOX2 cancer cells as they progressed in pseudotime." (PMID 36973297, 2023). "This indicates that gene amplification is dispensable for driving SOX2 overexpression in most cancer types." (PMID 37738673, 2023). "In multiple cancer models, AhR restricts stem cell proliferation by repressing pluripotency factors such as Oct-4, Sox2, c-Myc, and Nanog, and the expression or activation of AhR can promote differentiation in multiple cancer types." (PMID 37106727, 2023). "Taken together, these data suggest that TAZ and NANOG regulate cancer stemness and chemosensitivity via SOX2 and OCT4." (PMID 36646707, 2023). "In the context of ovarian cancer (OC), SOX2 assumes a predominant role in the maintenance of cancer stemness, particularly within spheroids, as evidenced by its higher expression levels." (PMID 38132318, 2023). "The knockdown of PFKFB3 inhibits the expression of cancer stemness markers such as CD133, ALDH1A1, CD44, Sox2, and ABCG2, which are also associated with chemotherapy resistance." (PMID 37919747, 2023). "The activation of STAT3 correlated with the increased expression of ALDH1, CD44, OCT4, and SOX2 in cancer cells." (PMID 37453969, 2023). "We also determined the HepG2 and MDA-MB-231 expression of the cancer stemness markers sox2 and Oct4 in the coculture models." (PMID 37370863, 2023). "The MSX2 interacts with SOX2 to control cancer stem cell-like characterization in oral squamous cell carcinoma (SCC)." (PMID 38110859, 2023). "We demonstrate that FOXA1 is an activator and NFIB is a repressor of SRR124–134 activity and SOX2 transcription in cancer cells, revealing a co-opting of the regulatory mechanisms involved in early development." (PMID 37738673, 2023). "Multiple studies have shown that Nanog and Sox2, two of the most important transcription factors in cancer stem cells, induce cancer cell metastasis in response to hypoxia." (PMID 37569414, 2023). "Olaparib treatment not only inhibited the development of mammospheroids but also downregulated the expression levels of cancer stemness markers, such as EpCAM, Nanog and Sox2." (PMID 36109724, 2022). "Because SOX2 has thousands of putative direct target genes along the genome, cancer cells hardly overcome these changes." (PMID 35921410, 2022). "Further, SNHG6 silencing reduced cancer stem cell markers Sox2, Oct4 and EZH2 in T47DTR cells, relative to parental T47D cells, and anti-miR-101 oligomers significantly (p<0.01) attenuated this effect." (PMID 36212408, 2022). "Research has indicated the involvement of SOX2 in spheroid formation, drug resistance, growth, and metastasis in several cancers of the breast, stomach, colon, and brain." (PMID 36551731, 2022). "Cancer stem cells have a specific gene signature, and the principal markers are SOX2, OCT4, and NANOG." (PMID 35965510, 2022).